NRAS (NRAS proto-oncogene, GTPase)
Diseases named in the same sentence as NRAS in open-access papers (continued):
Sharing a sentence is not in itself a finding about the gene and the disease.
lung adenocarcinoma (38 papers, 2009 to 2025). A carcinoma that arises from the lung and is characterized by the presence of malignant glandular epithelial cells. "Sasaki found only 1 case with NRAS mutation over 195 lung adenocarcinomas, underlining the rarity of these mutations." (PMID 40423070, 2025). "Codons 12, 13, or 61 are typically mutated in KRAS; similar mutations affect homologous genes HRAS and NRAS, though infrequently for lung adenocarcinomas." (PMID 29322935, 2017). "OncoMap also identified an HRAS mutation in a lung adenocarcinoma and an NRAS mutation in a colorectal adenocarcinoma." (PMID 19924296, 2009). "Three studies examined the features of NRAS-mutated lung adenocarcinoma." (PMID 40423070, 2025). "For the Ras proteins, KRAS/HRAS/NRAS all harbor highly recurrent mutations for residues p.G12/G13 that affect large fractions of pancreatic adenocarcinoma (PAAD), COAD, READ, lung adenocarcinoma (LUAD), and UCEC." (PMID 33875650, 2021). "Our study reports a retrospective analysis on OS rates observed in patients with lung adenocarcinoma harboring somatic mutations either in EGFR and KRAS genes, or in less frequently studied genes, such as BRAF, PIK3CA, NRAS, and HER2 (niche mutations)." (PMID 32082488, 2020). "1,760 lung adenocarcinoma patient blood samples were tested for analyzing mutations in EGFR, KRAS, NRAS, PIK3CA, HER2, BRAF and MET in cfDNA." (PMID 31749831, 2019). "The lung adenocarcinoma dataset SRA ERP001058 contains 41 tumors with known targetable or oncogenic mutations in 6 genes: EGFR, KRAS, NRAS, MET, BRAF and CTNNB1." (PMID 30255803, 2018). "Mutations in the RAS protein subfamily (HRAS, NRAS, KRAS) occur frequently in various types of cancer and have a relatively high frequency in lung adenocarcinomas." (PMID 26170901, 2015). "Therefore, the MASE‐CE assay for detecting KRAS, NRAS, BRAF mutations and MSI status can also be applied to patients with other cancers, including pancreatic and lung adenocarcinomas." (PMID 36583506, 2023). "For lung adenocarcinoma and endometrial carcinoma, we observed a cross-cancer effect for KRAS/NRAS-mutated cases as ATM levels are decreased, and MAPK_pT202_Y204, Claudin-7, S6_pS235_S236, and MEK1_pS217_S221 are increased in both histological tumor types consistently." (PMID 30442178, 2018). "DNA sequencing confirmed the presence of KRAS mutations, one of the most common driver mutations in lung adenocarcinoma, in three of the xenograft models and mutations in BRAF and NRAS, two less frequently occurring mutations associated with NSCLC, in two of the models." (PMID 22992329, 2012). "We took into consideration different rare mutations observed in BRAF, PIK3CA, HER2, and NRAS detected with a total frequency equal to 16.7% of patients with lung adenocarcinoma harboring somatic mutations, which is not a negligible prevalence if transposed to the entire population." (PMID 32082488, 2020). "As expected, EGFR, ITGA2, KRAS, MMP9, NRAS and MAPK13 had higher levels in lung adenocarcinoma than in normal lung tissues." (PMID 32210363, 2020).
metastatic tumors (37 papers, 2007 to 2025). "In Patient 14, the presence of the NRAS p.Q61K mutation in both the primary and metastatic tumors indicates they are clonally related." (PMID 39912776, 2025). "NRAS mutations were significantly more frequent in metastatic tumors (42.2%) compared to primary tumors (29.2%), while DICER1 mutations were more common in primary tumors (16.13% vs. 1.96% in metastases, p < 0.02)." (PMID 41590496, 2025). "In the 89 primary tumors, 26 NRAS mutations were identified (29.2%), while metastatic tumors exhibited 27 NRAS mutations (42.2%) among 64 samples." (PMID 41590496, 2025). "A genetic test was conducted inone patient with extensive metastatic disease and NRAS mutation was detected." (PMID 37726744, 2023). "This patient (subject #2) presented a BRAF H542Y mutation concomitant with an NRAS Q61R mutation in both the primary and the metastatic tumor in bone lesion." (PMID 33716974, 2021). "PCR-based Sanger sequencing showed KRAS mutations in metastatic tumor tissue of patients 2 (G12D), 3 (G12A) and 4 (G13D) and a NRAS mutation for patient 8 (G13R “c37G > C)." (PMID 31675944, 2019). "NRAS mutations were more frequent in metastatic tumors (42.4%) than primary tumors (29.2%)." (PMID 41590496, 2025). "When comparing any aberration with respect to primary and recurrent/metastatic sample types, SF3B1 (Fisher’s exact, P = 0.0057) and SPRED1 (Fisher’s exact, P = 0.02) mutations were mostly present in primary samples and NRAS aberrations were predominantly in recurrent/metastatic tumors." (PMID 31320640, 2019). "Oncologists reported testing for KRAS, NRAS, BRAF, HER2, and mismatch repair deficiency/microsatellite instability in 72%, 65%, 63%, 56%, and 66% of patients with metastatic disease, respectively." (PMID 37682042, 2023). "Currently, the workup for metastatic disease recommends the investigation of activating mutations in KRAS (exon 2, 3, or 4) or NRAS (exon 2, 3 or 4) and BRAF (V600E), as well MMR status." (PMID 34201502, 2021). "Within the metastatic disease setting, the presence of KRAS/NRAS mutations provides resistance to cetuximab and panitumumab, while BRAFV600E mutation predicts response to anti-EGFR targeted therapies in combination with a BRAF inhibitor." (PMID 34201502, 2021). "The metastatic tumor harbored a PHOX2B deletion and a missense mutation of NRAS (p.Gln61Lys), whereas an ALK mutation (p.Phe1174Leu) was detected only in the primary tumor." (PMID 28915622, 2017). "In contrast, NRAS-mutant patients were more likely to develop early nodal relapse and metastatic disease than the BRAF-mutant or WT cohort suggesting that they were at highest risk for disease progression and ultimately disease-specific mortality." (PMID 28797232, 2017). "For Patient 13, the different NRAS mutations in the primary and metastatic tumors suggest that the matched primary and metastasis are not clonally related." (PMID 39912776, 2025). "From a molecular perspective, specific patterns currently studied mainly in metastatic disease (like mutations of KRAS and NRAS genes) could be a useful tool for selecting high-risk patients." (PMID 39409934, 2024). "KRAS, NRAS, and BRAF mutations were always identical in both the primary and metastatic tumors." (PMID 25164765, 2014). "Ten other patients subsequently developed metastatic disease during the 10-year follow-up period (two of whom were positive for BRAF V600E and two of whom were positive for NRAS Q61R)." (PMID 38183457, 2024). "They found nine patients with different BRAF, NRAS, or TERT genotypic profiles between their metastatic tumors." (PMID 35887633, 2022).
metastatic tumors (continued). "BRAF exon 15 and NRAS exon 1 and 2 were investigated by Sanger sequencing of formalin fixed paraffin embedded (FFPE) primary tumors from time of diagnosis, and metastatic tumors collected before inclusion in the clinical trial." (PMID 31767937, 2019). "In the majority of multiple metastatic tumors, (BRAF:71.8%, NRAS:75%) metastases were relatively homogeneous regarding MAF." (PMID 31391014, 2019). "In primary tumors lacking KRAS, NRAS, or BRAF mutations, we did identify occult alterations in the EGFR/RAS pathway that in some patients were private to the metastatic tumor." (PMID 25164765, 2014). "The best approach to guide anti-EGFR treatment decision in SP-CRC with metastatic disease would be to test the metastatic tissue for KRAS and NRAS mutations, because it is not possible to be certain which primary SP-CRC lesion led to the metastasis without any additional study." (PMID 25859555, 2015). "Importantly, this observation was again confirmed in the metastatic tumors of TCGA (n = 287), with the T cell score showing a similar distribution in BRAF-mutated, NRAS-mutated, and double-WTs but showing no prognostic effect in NRAS-mutated tumors." (PMID 29664013, 2018).
mucosal melanoma (36 papers, 2014 to 2025). A melanoma that arises from a mucosal site. "In contrast, some cases of mucosal melanomas in humans and canines have shared gene mutations, with NRAS mutations found in 12% (179/1454) of human cases and 9.6% (11/115) of canine cases." (PMID 39408717, 2024). "NRAS mutation is found in approximately 15% of acral melanoma, but it is rarely seen in mucosal melanoma [8•]." (PMID 30675668, 2019). "Major driver mutations in mucosal melanoma were detected in NRAS, KRAS, NF1, PTEN, GNAQ, and KIT." (PMID 39564955, 2024). "Some studies indicate that the occurrence of a neuroblastoma RAS viral oncogene homolog (NRAS) mutation could be associated with mucosal melanomas in the vulvovaginal, anorectal, and head and neck regions." (PMID 39006602, 2024). "KIT mutations were found in approximately 15% of acral and mucosal melanomas, and BRAF or NRAS mutation was found in approximately 10–15% of acral melanoma, but was less frequent in mucosal melanoma [8•, 9]." (PMID 30675668, 2019). "Gene set enrichment analysis (GSEA) using the cancer single‐cell state atlas (cancerSEA) database revealed that angiogenesis, epithelial–mesenchymal transition (EMT), invasion and metastasis signatures were significantly enriched in NRAS mutant mucosal melanoma." (PMID 39757723, 2025). "This study analyzed a subset of cases by Sanger sequencing, and others by next-generation sequencing (NGS); and proposed NRAS mutation as a predictor of worse survival, independent of stage in all mucosal melanomas." (PMID 35642348, 2023). "Activating mutations of NRAS and c-kit appear to be absent in canine mucosal melanoma, in contrast to human mucosal melanoma, where these genes are mutated in 15% of tumors." (PMID 29056717, 2016). "Molecular epidemiology studies indicated that the mutation pattern of mucosal melanoma is fundamentally different as compared to cutaneous locasion since KIT is the most frequently involved oncogene (15–25%) followed by a much less frequent involvement of BRAF, NRAS (<10%)." (PMID 31848942, 2020). "Indeed, the specific NRAS and BRAF mutants found in mucosal melanoma could be linked to their particular effects on protein activity during mucosal melanocyte transformation, adding an additional layer of complexity." (PMID 31398831, 2019). "We catalogued alterations of the NRAS and BRAF genes in mucosal melanoma and showed that they represent a significant portion of mutations (20%) in these tumors." (PMID 31398831, 2019). "For BRAF/NRAS wild-type PARM where immunotherapy access is limited, adjuvant temozolomide-cisplatin remains a clinically viable consideration, supported by prospective survival data in mucosal melanoma." (PMID 41458594, 2025). "NRAS and NF1 play a role in the molecular landscape of mucosal melanoma." (PMID 35159047, 2022). "NRAS and NF1 are confirmed to play a role in mucosal melanoma." (PMID 35159047, 2022). "When the mucosal melanoma is triple (BRAF, NRAS, NF1)-negative, KIT is the most commonly mutated gene in vulvovaginal melanomas, while APC and KRAS are detected mainly in sinonasal and anorectal melanomas, respectively." (PMID 34571863, 2021). "A single exception has been recently reported concerning a case of metastatic mucosal melanoma harboring the GNAQQ209P mutation in exon 5, with no mutations of the BRAF, NRAS, or c-KIT genes." (PMID 25695059, 2015). "The mutations of the KIT gene are found with greater frequency for mucosal melanoma (30%), unlike for BRAF and NRAS genes." (PMID 31274706, 2020).
Noonan syndrome (36 papers, 2014 to 2026). "Proband 26 carried a de novo G12D variant in NRAS that is pathogenic in Noonan syndrome according to ClinVar (Variation ID: 39648); Noonan Sd can present with SLE17." (PMID 40386946, 2025). "Mutation in NRAS resulting in an I24N amino acid substitution was identified in an individual bearing typical Noonan syndrome features." (PMID 35713744, 2022). "In contrast, germline NRAS mutations have been identified in patients with Noonan syndrome, which is characterized by short stature, congenital heart disease, lymphatic abnormalities, chest deformity, and predisposition to malignant tumors." (PMID 31511039, 2019). "This corroborates the finding that patient’s with Costello Syndrome (HRAS germline mutation), Noonan Syndrome (NRAS, KRAS, PTPN11 germline mutations) and Neurofibromatosis (NF1 germline mutation) all have increased risk of developing fusion-negative RMS." (PMID 25768946, 2015). "For example, in Noonan syndrome, NRAS or KRAS can be mutated at various positions along their coding sequences in the germline." (PMID 26274561, 2015). "Noonan syndrome (NS) is a RASopathy most frequently associated with mutations in HRAS, NRAS, KRAS, and RRAS2." (PMID 41517739, 2026). "Mutations associated with Noonan syndrome alone include CBL, BRAF, KRAS, LZTR1, MAP2K1 (MEK1), NRAS, PTPN11, RAF1, RIT1, SOS1 and SOS2." (PMID 38550930, 2023). "The LM subgroup encompasses all patients with CBL syndrome and Noonan syndrome with MPD, as well as patients with somatic NRAS mutations and low-risk features." (PMID 29259247, 2017). "On the other hand, our patient and other cases with pure chromosome 1p13.2microdeletions and hemizygosity for NRAS reviewed by us from theliterature or from the DECIPHER database all seemed to present several clinical featuresof Noonan Syndrome." (PMID 27561113, 2016). "In addition to the PTPN11 mutations in the RAS‐MAPK signaling pathway, including KRAS, SOS1, RAF1, SHOC2, NRAS, BRAF and CBL, can also cause Noonan syndrome." (PMID 37525886, 2023). "In addition, we verified by exomeanalysis that the patient did not have any pathogenic variants in the genes associatedwith Noonan Syndrome and other rasopathies (PTPN11,SHOC2, KRAS, CBL,SOS1, RAF1, HRAS,NRAS, RASA1, SPRED1,BRAF, MAP2K1, MAP2K2, RIT1 andRRAS)." (PMID 27561113, 2016). "In the absence of SH3BP2 mutation in an individual considered to have Cherubism, genetic screening for mutations in genes implicated in Noonan syndrome (PTPN11, SOS1, RAF1, KRAS, NRAS, and BRAF), NF1, and craniofacial cutaneous syndrome (BRAF, MAP2K1) should be undertaken." (PMID 25409853, 2014). "However, NRAS p.Q61R mutation has never been identified in Noonan syndrome patients, suggesting that patients with germline p.Q61R mutation do not survive to birth because of its strong activation of the downstream pathway." (PMID 31511039, 2019). "Over the years, several other genes involved in Noonan syndrome (KRAS, SOS1, RAF1, MAP2K1, BRAF, NRAS, RIT1, and LZTR1) have been identified, acting at different levels of the RAS-mitogen-activated protein kinase pathway." (PMID 38254922, 2023).
Noonan syndrome (continued). "RAS paralogs (HRAS, NRAS and KRAS) are of major interest in biology because they are involved in developmental disorders (e.g., Costello and Noonan syndromes) and in a broad variety of human neoplasia." (PMID 33187149, 2020). "This contrasts with children without Noonan Syndrome bearing somatic RAS mutations in PTPN11, NRAS and KRAS, who account for a significant proportion of JMML cases." (PMID 35409034, 2022). "An analysis of neonatal blood spots has identified such somatic RAS pathway mutations (most commonly in PTPN11, NRAS and KRAS) in 38% of children (n = 34) without Noonan Syndrome but presenting with JMML at a median age of 1.5 years." (PMID 35409034, 2022). "While the majority of those with Noonan Syndrome carry germline mutations in RAS pathway genes (e.g., PTPN11, KRAS, NRAS, SOS-1, RAF1, BRAF), not all develop JMML." (PMID 35409034, 2022).